CTSB (cathepsin B)
Diseases named in the same sentence as CTSB in open-access papers (continued):
Sharing a sentence is not in itself a finding about the gene and the disease.
cancer (continued). "While these studies propose cathepsin B as a potential biomarker for predicting cancer progression in OSCC, they acknowledge limitations, such as small sample sizes and the absence of patients with benign lesions or other chronic inflammatory oral diseases." (PMID 38500921, 2024). "These CDs were utilized to develop a cancer-targeting and CTSB stimulus-responsive ratio metric nanoprobe, AS1411–Ce6–CQDs." (PMID 39339503, 2024). "Cancer cells often release the lysosomal protease cathepsin B for collagen degradation in the ECM by vesicular exocytosis." (PMID 38141765, 2024). "Development of cathepsin B inhibitors: The development of cathepsin B inhibitors is an active area of research due to their potential as a therapeutic target for cancer and other diseases." (PMID 38500921, 2024). "In cancer, this intracellular protease exhibits high levels of expression, which often induce secretion of Cathepsin B from cancer cells at the invasive edges of tumors." (PMID 38612886, 2024). "The encapsulation process ensured high drug loading efficiency, stability under physiological conditions, and controlled release of the prodrug in response to cathepsin B, an enzyme overexpressed in cancer cells." (PMID 39274842, 2024). "In cancer cells, overexpressed cathepsin B specifically cleaves the -FRRG- part of SMAC-FRRG-DOX, releasing DOX." (PMID 39274842, 2024). "Recognized for its significance in tumorigenesis, angiogenesis, invasion, and metastasis, cathepsin B emerges as a crucial player in cancer progression." (PMID 38500921, 2024). "Inhibition of cathepsin B activity: Inhibition of cathepsin B activity has been a research focus due to its potential role in cancer therapy." (PMID 38500921, 2024). "Cathepsin B, a cysteine protease, plays a crucial role in intracellular proteolysis and is overexpressed in several human cancers, indicating its potential involvement in tumorigenesis." (PMID 38500921, 2024). "Recent studies have revealed the role of several cathepsins in promoting or inhibiting various cancers (e.g., lung, ovarian, thyroid, and colorectal), including cathepsin B (CTSB), cathepsin L (CTSL), cathepsin G (CTSG), and cathepsin S (CTSS)." (PMID 38883596, 2024). "The expression and trafficking patterns of cathepsin B undergo frequent alterations in cancer, with its plasma membrane and secreted forms believed to participate actively in invasion and metastasis." (PMID 38500921, 2024). "Oncetaken up by MMP-2 and cathepsin B overexpressing cancer cells (e.g.,the A549 cell line), cascaded hydrolysis releases the photoactiveDSBDP and restores its photodynamic activities." (PMID 38422393, 2024). "Cathepsin B, L, and S, for example, actively facilitate cancer metastasis by promoting the degradation of the extracellular matrix, thereby enhancing the invasive potential of cancer cells." (PMID 39122455, 2024). "Targeting cathepsin B as a therapeutic strategy for cancer treatment faces several challenges and requires further research." (PMID 38500921, 2024). "In a proteome array analysis of 84 human cancer-related proteins we identified several proteins being solely expressed by the T18 stromal cells like cathepsin B, D and S, interleukins, EGFR and MMP-2 as well as progranulin, Axl and PAI-1." (PMID 39695086, 2024). "Cathepsin B is one of the most widely overexpressed cysteine cathepsins in various cancers, and it is involved in the degradation of fibronectin, type IV collagen, and laminin, which leads to cell migration, invasion, and angiogenesis." (PMID 38398021, 2024). "Cathepsin B, a lysosomal cysteine protease, has emerged as a potential key player in the intricate landscape of cancer biology." (PMID 38500921, 2024). "Aberrant expression/activityof CTSB has been employed as a pathological biomarker in the designof theranostic agents for cancer-selective imaging and treatment." (PMID 38422393, 2024).
cancer (continued). "PYK2 activation has been reported previously to regulate cathepsin-B secretion from human primary macrophages during the immune response and their activation have both shown to enhance cancer cell invasion and metastasis." (PMID 37055381, 2023). "In cancer, cathepsin B is found in lysosomes as well as in vesicles, throughout the cytoplasm and at the cell periphery." (PMID 36579638, 2023). "The SMAC-P-FRRG-DOX is subsequently cleaved to SMAC-P and DOX in cathepsin B-overexpressing cancer cells." (PMID 37845762, 2023). "For the MSC-mediated cancer therapy, cathepsin B-cleavable and pro-apoptotic prodrugs (SMAC-P-FRRG-DOXs) were encapsulated into 10PS, which had been determined as the optimal LNP for intratumoral administration, resulting in ApoLNPs." (PMID 37845762, 2023). "As expected, 4T1 cancer cells expressed 5.6-fold higher cathepsin B compared to normal cells of rat cardiomyocytes (H9C2), indicating that the prodrug of SMAC-P-FRRG-DOX in ApoLNPs can be specifically cleaved via cancer cell-overexpressed cathepsin B." (PMID 37845762, 2023). "The SMAC-P-FRRG-DOX prodrug was designed to be specifically cleaved to release SMAC-P and free DOX in response to cancer cell-overexpressed cathepsin B." (PMID 37845762, 2023). "Cathepsin B cleaved the linker between CyA-P-CyB in cancer cells, which they fluoresced in the near-infrared region via the Förster resonance energy transfer mechanism." (PMID 36986636, 2023). "Targeting and controlling cathepsin B in cancer patients have opened a new avenue for designing pharmacological approaches in cancer treatment." (PMID 37111617, 2023). "CTSB plays a central role in a variety of pathological processes, including initiation, proliferation, growth, angiogenesis, and metastasis of malignant tumors." (PMID 37576397, 2023). "In this review, we summarized recent technologies applied to cancer disease that base their working mechanism on CtsB cleavage." (PMID 37514035, 2023). "A docetaxel-loaded cathepsin B-responsive nanoconjugate was constructed for cancer chemo-immunotherapy." (PMID 36986636, 2023). "Increased CTSB expression occurs at the invasive margin in many tumors, and degradation of the ECM by CTSB is a critical step in cancer cell invasion and metastasis." (PMID 37576397, 2023). "Since high cathepsin B levels are directly related to cancer progression, cathepsin B has been proposed as a marker in cancer patients." (PMID 37233478, 2023). "Cathepsin B is an important target in cancer research and has been widely studied for the past 20 years." (PMID 37111617, 2023). "The cell-internalized ApoLNPs induced cancer-specific and pro-apoptotic cell death due to cancer cell-overexpressed cathepsin B cleavage mechanism of SMAC-P-FRRG-DOX." (PMID 37845762, 2023). "The ratio of CTSB/cystatin C in the serum is clinically significant in the prognosis of cancer patients." (PMID 37576397, 2023). "Cathepsin B is involved in many physiological processes, such as cancer migration, angiogenesis, and metastasis." (PMID 37111617, 2023). "Most likely, the reduction in cathepsin B activity observed in cisplatin-treated tumors is a result of the cytotoxic effect on cancer cells, leading to a lower release of cathepsin B by the cells." (PMID 37568601, 2023). "PNP specifically releases free doxorubicin into the nucleus of cancer cells via the sequential enzymatic cleavage of CTSB and intracellular proteases." (PMID 37576397, 2023). "CTSB has been reported as a potential prognostic marker for BC where it is involved in cancer progression and invasion." (PMID 38213901, 2023). "Much recent pharmacological research has been focused on targeting overexpressed cathepsin B in cancer cells." (PMID 37111617, 2023). "In cancer cells, CTSB is shuttled to the plasma membrane, where it activates receptor-bound urokinase-type plasminogen activator (pro-uPA)." (PMID 37576397, 2023).
cancer (continued). "Incorporating a cancer-targeting recognition moiety would enable a robust ratiometric fluorescence technique to report CTSB activity." (PMID 36986879, 2023). "Cancer-specific and pro-apoptotic SMAC-P-FRRG-DOX prodrugs were encapsulated into LNPs to form ApoLNPs, and the ApoLNPs were proven with their s pro-apoptotic property and cathepsin B specificity in cancer cells." (PMID 37845762, 2023). "The GFLG peptide increased the stability of the system and after AuNR–LAX internalization into cancer cells, CtsB-mediated cleavage induced DOX release." (PMID 37514035, 2023). "Numerous cathepsin B inhibitors have been developed and are under investigation as potential cancer treatments." (PMID 37111617, 2023). "Knockdown or selective inhibition of cathepsin B suppresses cancer invasion and metastasis to the lung and bone, whereas an increased cathepsin B expression and activity promotes metastatic spread." (PMID 36002710, 2023). "MZF1 is an oncogenic transcription factor that is activated by p95ErbB2 and is positively regulating lysosome-mediated invasion of cancer cells via cathepsin B expression." (PMID 37420029, 2023). "There is also a method to enhance the release of chemotherapeutic drugs, because cathepsin B is overexpressed in cancer cells, and cathepsin B can catalyze the hydrolysis of GFLG peptide." (PMID 37284316, 2023). "Cathepsin B inhibitors are being actively investigated as potential anticancer agents due to their role in cancer cell invasion and migration." (PMID 37111617, 2023). "The inhibition of cathepsin B by phytocystatins has revealed their potential to control health issues such as cancer and inflammatory diseases." (PMID 37239031, 2023). "The ApoLNPs show a high therapeutic effect specifically to cathepsin B-overexpressing cancer cells with 6.6 μM of IC50 value while its IC50 against normal cells is 230.7 μM." (PMID 37845762, 2023). "In malignant tumors, the expression of cathepsin B is highly upregulated and mature cathepsin B is secreted to the cell surface where it can degrade ECM proteins." (PMID 35239671, 2022). "On the other hand, DKK1, CTSB, CTSD, BCLX, CSF1, and CAPG are associated with the metastatic potential of cancer." (PMID 35745691, 2022). "Simultaneously, the autophagy cascade resulted in being impaired due to cathepsin B and L inhibition that also contributed to a reduction in cancer cell migration." (PMID 36364419, 2022). "Here, we comprehensively profiled the expressions and distributions of CTSB/L in human normal tissues, cancer tissues, and cell lines." (PMID 35155389, 2022). "Cathepsin B (CTSB) is a lysosomal protease, and several human cancers are reported to have elevated expression of CTSB, which has also been suggested as a potential cancer biomarker." (PMID 36080733, 2022). "We developed a new hydrophilic PS prodrug to selectively target cathepsin B, which is highly upregulated in several pathologies, including immune disorders, cardiovascular diseases, and cancer." (PMID 35631388, 2022). "Studies have shown that in some malignant tumors and precancerous lesions, the expression of cathepsin B (CTSB) is highly upregulated." (PMID 35186883, 2022). "Cathepsin B (Cat-B) belongs to the family of lysosomal cysteine proteases, which are closely related to the development of cancer, and it is a typical stimulator, as its concentration in a variety of tumors is 3 to 9 times higher than that in normal tissues." (PMID 36365164, 2022). "Then, the DOX molecules released from PD-NPs in the cathepsin B-overexpressed cancer cells induce ICD, which promote high DAMP signals for DC maturation and cytotoxic T lymphocyte activation." (PMID 35265195, 2022).
cancer (continued). "Perhaps these amino acids play a critical role in the synthesis of nucleic acids translated to proteins like Cathepsin B in cancer cells to foster metastasis." (PMID 36574159, 2022). "In this case, targeting is achieved not via specific binding but via specific peptide cleavage by cathepsin-B, an enzyme overexpressed by cancer cells, with consequent disassembly of the nanoparticles and release of doxorubicin." (PMID 35626078, 2022). "With high cathepsin B-specificity, F68-FDOX induce a potent cytotoxicity preferentially in cancer cells, whereas their cytotoxicity is greatly minimized in normal cells with innately low cathepsin B expression." (PMID 36195911, 2022). "Upon cellular uptake, the NPs were cleaved to obtain pro-apoptotic SMAC and cytotoxic DOX specifically in cancer cells that overexpress cathepsin B, inducing a synergic effect of the combined molecules in a metastatic LC model." (PMID 35163777, 2022). "We suppose that a lower inhibitor activity in the surrounding cancer accompanied by enhancing the presence of CtsB in the cancer core can facilitate the cancer cell spreading." (PMID 35563761, 2022). "The secretion of CTSB is significantly increased in cancer cells and are active and stable in acidic environments and neutral acidity." (PMID 36132145, 2022). "Hyaluronidase, esterase, matrix metalloproteinases, and cathepsin B are forms of enzymes that are highly expressed in cancer tissue and are thought to be suitable activators." (PMID 35631699, 2022). "Due to frequent gene mutations in tumors, the mutative status of CTSB and CTSL were analyzed in pan-cancers." (PMID 35155389, 2022). "CTSB is produced constitutively and was identified as a housekeeping protein, and was highly upregulated in malignant tumors." (PMID 36132145, 2022). "Next, the higher expression of CTSB and STFA mRNAs was associated with the cases of cancer affecting both kidneys compared to patients with single kidney involvement (right or left kidney)." (PMID 35563761, 2022). "DARPins (designed ankyrin repeat proteins) have been shown to block CTSB activity in tumors and have been successfully applied for optical imaging in cancer models." (PMID 35872750, 2022). "Here, we conducted a profiling analysis of CTSB/L expressions in healthy individuals and patients with pan-cancers by using transcriptomic, genomic, and epigenomic data." (PMID 35155389, 2022). "CA074 is a selective inhibitor of CTSB, has been developed as a promising agent for treatment of different cancers." (PMID 36713420, 2022). "Overall, it is suggested that the overexpression of CTSB/L not only predicts a poor prognosis of cancers but also increases the susceptibility of SARS-CoV-2, leading to unsatisfied clinical outcomes of cancer patients." (PMID 35155389, 2022). "CtsB overexpression has been detected in many types of malignant tumors (e.g., prostate, pancreatic cancers, and melanoma), including RCC, indicating its potential value as a therapeutic target." (PMID 35563761, 2022). "To address those general issues of cysteine cathepsin involvement in cancer progression, we focused on cathepsin B (CTSB)." (PMID 32385587, 2021). "Cathepsin B is a cysteine protease which presents almost exclusively in the lysosomal compartment in healthy mammals, and is overexpressed in multiple cancer types." (PMID 34641391, 2021). "These liposomes are degraded by cathepsin B enzyme, which is overexpressed in several cancer cells types and exhibits an effective anticancer effect on Hep G2 cells in vitro and inhibit cancer cell proliferation in a zebrafish model." (PMID 35011376, 2021). "Cathepsin B is involved in cancer invasion and metastasis, and it is overexpressed in cancer tissue." (PMID 33673582, 2021). "Cathepsin B is another target for enzyme-responsive NPs and has many roles in cancer progression, such as cell growth, cell migration, and angiogenesis." (PMID 34834387, 2021).
cancer (continued). "To ensure that the cytotoxic cargo will be released only into the cancer cells, we used valine–citrulline (vc) linker cleaved by cathepsin B in the lysosomal compartments, and well characterized in clinical studies." (PMID 34867353, 2021). "We analyzed the proteome secreted by co-cultures of cancer cells and macrophages with variable genotypes of CTSB and the closely related CTSZ in vitro." (PMID 32385587, 2021). "Cathepsin B (CatB) is chosen as the cancer biomarker, which is commonly overexpressed in various cancer cells, such as breast cancer, colorectal cancer, melanoma, and prostate cancer." (PMID 34006860, 2021). "Cathepsin B, a cysteine protease presents in late endosome and lysosome compartments in mammals, is also overexpressed in many cancer cells." (PMID 34067144, 2021). "Second, MMAE is released only upon enzymatic cleavage by cathepsin B, which is upregulated in the lysosomes of cancer cells." (PMID 33782486, 2021). "Such destabilization of lysosomes specifically occurs in cancer cells, followed by the release of lysosomal enzymes, including Cathepsin B and Cathepsin D. Cathepsin B mainly contributes to TNF‐α‐induced necrosis, while Cathepsin D evokes apoptosis." (PMID 34523247, 2021). "Previous studies have reported that siRNA-induced downregulation of CTSB inhibited EMT in other cancer cell lines." (PMID 33333840, 2020). "Such high expression of cathepsin B in many different cancers led to the assumption that this enzyme played a fundamental role in progression of these tumors." (PMID 32050622, 2020). "Aberrant regulation of cathepsin B expression correlates with the invasive and metastatic phenotype of cancer." (PMID 33335896, 2020). "A negative correlation of cathepsin B expression and laminin in gastric and colorectal cancer suggests the involvement of cathepsin B in ECM remodeling." (PMID 32727598, 2020). "Our results show that ISL can decrease cathepsin B protein expression to suppress p62 accumulation, increasing autophagy-mediated apoptosis and decreasing cancer cell proliferation-related Ki67 expression." (PMID 32164337, 2020). "In order to increase the chemotherapeutic potential of DOX and limit its toxicity, we used a Cathepsin B (Cat B)-sensitive prodrug concept for its targeted release since this enzyme is frequently overexpressed in cancer cells." (PMID 32962018, 2020). "Essentially, this notion is limited to findings showing that cathepsin B and legumain can be found in the nucleus of cancer cells and there is also data showing that cathepsin L can be localized in the nucleus of embryonic stem cells." (PMID 32709152, 2020). "The upregulation of cathepsin B occurs in premalignant lesions and various pathological conditions, as well as cancer." (PMID 33233633, 2020). "Increasing the expression of cathepsin B in cancer cells can enhance the metastatic ability of cancer cells." (PMID 33335896, 2020). "As such, several studies have attempted to develop therapeutic strategies that target cancer cells expressing cathepsin B." (PMID 32937915, 2020). "The peptide Ad-CGKRK-GFLG-EE-HAIYPRH(T7) with a guest molecule Ad termination and cathepsin B (CTSB) (overexpressed in cancer cells)-cleavable linker GFLG was developed, and Ce6 was conjugated to the host molecule b-Cyclodextrin (b-CD) through an amide bond." (PMID 32641993, 2020). "GLFG/Dox were found to be sensitive to degradation by cathepsin B and exerted a more pronounced anticancer effect in Hep G2 cells and in a cancer cells-injected zebrafish model in vivo." (PMID 32937915, 2020). "Cancer studies have shown that cathepsin B is related to cancer cell proliferation, and its ability to break down the cell base membrane can increase cancer cell invasion." (PMID 32164337, 2020). "Cathepsin B is thought to be involved in the diagnosis, treatment and prognosis of malignant tumors." (PMID 33335896, 2020).